DUSP1 (dual specificity phosphatase 1)
Diseases named in the same sentence as DUSP1 in open-access papers (continued):
Sharing a sentence is not in itself a finding about the gene and the disease.
infectious disease (2 papers, 2023 to 2024). A disorder directly resulting from the presence and activity of a microbial, viral, or parasitic agent in humans. "In fact, DUSP1 is sensitive to bacterial LPS in macrophages, suggesting that DUSP1 is required for the balance of inflammatory responses in infectious diseases." (PMID 39606227, 2024).
adenocarcinoma (1 paper, 2013). A common cancer characterized by the presence of malignant glandular cells. "Finally, 10 genes were obtained, among which, four genes, dual-specificity mitogen activated protein (MAP) kinase phosphatase 1 (DUSP1), Zimp7, EST NP_937824 and XM_498632, were expressed at a higher level in the stage I adenocarcinoma samples than in those of stages II and IIIA." (PMID 24137407, 2013).
gastrointestinal neoplasms (1 paper, 2022). "According to these findings, DUSP1 was strongly associated with the muscle atrophy of cachexia in gastrointestinal neoplasms." (PMID 36387242, 2022). "As a result of our findings, DUSP1 was expected to be a specific target for preventing and treating cachectic muscle atrophy in patients with gastrointestinal tumor." (PMID 36387242, 2022). "The clinical significance of DUSP1 was then investigated in the skeletal muscle tissues of patients with gastrointestinal tumor." (PMID 36387242, 2022).
kidney diseases (1 paper, 2022). "When we assessed the expression of DUSP1 according to specific kidney disease types, all categories of profiled diseases showed significantly lower expression of DUSP1 than the nephrectomy controls." (PMID 35488446, 2022). "Among the DEGs, we performed experimental studies with DUSP1, which was universally expressed at low levels in injured kidney tubulointerstitial tissues in various kidney diseases." (PMID 35488446, 2022). "Our experiments with DUSP1 suggested that the transcriptome profiling results may lead to the identification of a potential biomarker for kidney diseases." (PMID 35488446, 2022).
neuromuscular disease (1 paper, 2025). "Thus, the DUSP1 and JNK pathways are of interest in neuromuscular diseases other than SBMA." (PMID 40474744, 2025).
DUSP1 also shares sentences with these, for which no sentence is quoted: colitis (9 papers); steatosis (4); acute kidney injury (3); fibrosis (3); inflammation (3); sarcopenia (3); ulcerative colitis (3); Cardiovascular Diseases (2); fungal infection (2); glucose metabolism disorder (2); hypertrophy (2); idiopathic pulmonary fibrosis (2); IgA nephropathy (2); mental disorder (2); metastatic melanoma (2); multiple sclerosis (2); overnutrition (2); Periodontal Disease (2); pterygium (2); septic peritonitis (2); small cell lung carcinoma (2); abdominal aortic aneurysm (1); abscesses (1); acute myelogenous leukemia (1); acute myocardial infarction (1); adenoma (1); African trypanosomiasis (1); age (1); airway hyperresponsiveness (1); Allergy (1).
A further 104 diseases each share a sentence with DUSP1 in 1 paper.